MRPL46 (mitochondrial ribosomal protein L46)
Synonyms: C15orf4; LIECG2; P2ECSL; mL46
Tractability: Small molecule: a structure with a bound ligand is known. PROTAC: ubiquitination databases record sites on it; its protein half-life has been measured.
Gene: Protein-coding gene on chromosome 15 (88,459,468 to 88,467,420, reverse strand). Ensembl gene ENSG00000259494.
Subcellular location: Mitochondrion
Subcellular location (Human Protein Atlas): Mitochondria; Cell Junctions; Cytosol; Nucleoplasm
Pathways (Reactome):
Metabolism of proteins: Mitochondrial ribosome-associated quality control; Mitochondrial translation elongation; Mitochondrial translation initiation; Mitochondrial translation termination
Gene Ontology:
Molecular function: structural constituent of ribosome
Biological process: mitochondrial translation
Cellular component: mitochondrial large ribosomal subunit; mitochondrion; mitochondrial inner membrane
Genetic constraint (gnomAD): Loss-of-function variants: 26 observed, 31.92 expected, observed/expected ratio (o/e) 0.81, 90% interval 0.6 to 1.13. The upper end of that interval is the gene's LOEUF score, 1.13, which puts it in group 4 of 6, group 1 being the genes least tolerant of losing a copy. Missense variants: 395 observed, 356.76 expected, observed/expected ratio (o/e) 1.11, 90% interval 1.02 to 1.2. Synonymous variants: 159 observed, 148.86 expected, observed/expected ratio (o/e) 1.07, 90% interval 0.94 to 1.22.
Homologues: Orthologues: chimpanzee MRPL46 (99% identical), macaque MRPL46 (94% identical), pig MRPL46 (85% identical), dog MRPL46 (85% identical), guinea pig MRPL46 (84% identical), mouse Mrpl46 (81% identical), rat Mrpl46 (80% identical), rabbit MRPL46 (79% identical), tropical clawed frog mrpl46 (56% identical), zebrafish mrpl46 (44% identical), Drosophila melanogaster mRpL46 (34% identical), Caenorhabditis elegans mrpl-46 (26% identical).
Diseases named in the same sentence as MRPL46 in open-access papers:
MRPL46 is named in the same sentence as 10 diseases in open-access papers, as found by Europe PMC text mining. Sharing a sentence is not in itself a finding about the gene and the disease. The quoted sentences say what the papers report.
ovarian tumor (1 paper, 2024). "The role of genes encoding such proteins, LUC7L2, MRPL46, MRPL14, PARP4, STRAP, and PAPOLA, in ovarian tumor development has already been investigated in the literature." (PMID 39456618, 2024).
MRPL46 also shares sentences with these, for which no sentence is quoted: depression (3 papers); attention deficit-hyperactivity disorder (1); autism spectrum disorder (1); bipolar disorder (1); breast carcinoma (1); generalized anxiety disorder (1); obsessive-compulsive disorder (1); ovarian carcinoma (1); schizophrenia (1).